AFP (alpha fetoprotein)
Diseases named in the same sentence as AFP in open-access papers (continued):
Sharing a sentence is not in itself a finding about the gene and the disease.
cancer (continued). "AFP mRNA was detected primarily in the cytoplasm of cancer cells with variable staining intensity." (PMID 33824478, 2021). "The patients with HBV-related HCC were significantly younger, had better Child-Pugh scores, lower FIB-4 index and Mac-2 binding protein glycosylated isomers (M2BPGi) levels, more progressive cancer stage, and higher alpha-fetoprotein (AFP) levels than those with HCV-related HCC." (PMID 34885089, 2021). "While some cancer signature proteins are indeed increased as in the case of AFP." (PMID 34035320, 2021). "Interestingly, serum AFP and cytoplasmic AFP show different, even opposite, roles in the cancer progression of HCC." (PMID 34680245, 2021). "Cancer cells express AFP, which is usually found in the nuclei." (PMID 33607799, 2021). "Notably, GP73 has been indicated to be highly expressed in pathological tissues and serum derived from early cancer patients, which manifests higher diagnostic sensitivity and specificity than classic HCC biomarker alpha-fetoprotein (AFP)." (PMID 34950590, 2021). "AFP is known to selectively bind and to be internalized by a wide range of cancer cells." (PMID 34648110, 2021). "Detection of elevated AFP combined with hypoechoic nodule or mass is essential in the diagnosis of HCC with 82.6% sensitivity and 70.4% specificity, and confirmation of higher cancer risk in DM2 patients encourages special attention in this group." (PMID 33652777, 2021). "Therefore, vaccines against AFP inhibit the growth of AFP receptor-positive cancer cells and prolong patient survival time." (PMID 33898423, 2021). "Alongside ALBI grade, univariable analyses of survival revealed CTP class (p < 0.01), BCLC stage (p = 0.04), AFP > 400 ng/mL (p = 0.02), achievement of radiologic disease control (p < 0.001) and provision of further anti-cancer therapy post-ICI (p < 0.001) as significant prognostic factors for OS." (PMID 32664319, 2020). "In addition, the level of Bcl‐2 in cancer tissues of patients with low AFP serum was lower than that of patients with high serum AFP." (PMID 33090723, 2020). "However, the contribution of IL-13/STAT6 and YAP1, together with serum AFP, are proven to have the upper hand in predicting cancer development in NASH." (PMID 32283835, 2020). "Evidence suggests that AFP may not only be a biomarker for cancer diagnosis, but also play functional roles in tumorigenesis." (PMID 31897235, 2020). "Therefore, we selected DTA as a therapeutic gene for gene therapy of these heterogeneous tumors to inhibit protein synthesis, which has been used in various cancers, and used an AFP promoter to control its expression within the AFP-expressing HCC cells." (PMID 32085552, 2020). "AFP-derived peptide fragments have been developed to suppress the growth of human cancer cells." (PMID 33009373, 2020). "We successfully employed the Au NR-QDs to fabricate nano-sensors for detecting a cancer biomarker of alpha fetoprotein with a limit of detection of 0.30 ng/mL, which displays that the sensitivity of the Au NR-QDs nano-sensor was effectively improved compared with the Au NRs based plasmonic sensing." (PMID 32121506, 2020). "Next, we tried to find out what leaded to AFP re-expression in cancer." (PMID 31897235, 2020). "Therefore, uncovering the molecular features of AFP high subtype of HCC is urgently needed for personalized cancer therapy." (PMID 32350243, 2020). "However, the most promising results of AFP cancer immunization were achieved through production of epitope-optimized AFP, which effectively activated CD8+ T cells and generated potent antitumor effects in HCC mouse model." (PMID 32899197, 2020). "Fraction AFP-L3% (i.e., AFP fraction binding to Lens culinaris agglutinin—LCA) may be used to distinguish between benign and malignant tumours (i.e., a predictive biomarker), but the same form of AFP has been produced by HCC." (PMID 31652641, 2019). "Some conditions, like pregnancy or cancer, can generate high AFP levels in serum." (PMID 31258835, 2019).
cancer (continued). "AFP is overexpressed in HCC cells, and is strongly associated with aggressiveness of cancer cells." (PMID 31581132, 2019). "AFP can inhibit the maturation and induce apoptosis of DC cells, so that cancer cells could escape the immune surveillance." (PMID 29805966, 2018). "Recently, clinical trials showed that nivolumab, a programmed cell death protein-1 (PD-1) immune checkpoint inhibitor, produced durable objective responses for treatment of HCC, indicating the possibility of combining nivolumab with AFP to suppress the proliferation of cancer cells." (PMID 29805966, 2018). "A large proportion of patients with early-stage HCC or other malignant tumors may also show an elevated serum AFP level." (PMID 28794477, 2017). "Furthermore, serum ferritin measurements have been combined with more traditional cancer biomarkers such as CEA (carcinoembryonic antigen) and AFP (alpha-fetoprotein) for use as a diagnostic and/or prognostic marker in several types of cancer." (PMID 28160568, 2017). "The fetal yolk sac and fetal liver generate high levels of AFP, and malignant tumors derived from the hepatic diverticulum may also elevate the serum AFP levels, including stomach, pancreas, and biliary tract." (PMID 28031532, 2017). "Owing to its high specificity and affinity for AFP antigen in hepatic cancer cells, anti-AFP monoclonal antibody (antiAFPMcAb) can carry various “warheads” such as chemotherapy agents, radionuclides, or toxins to selectively attack AFP-positive cancer cells." (PMID 26981334, 2016). "Our data suggest that HSP70-P/AFP-P may be used as a therapeutic approach in the treatment of AFP-expressing cancers." (PMID 27713135, 2016). "Alpha fetoprotein, a novel member of regulation the signal transduction involve in cancer cells malignant behaviours was discovered recently 17, 21, but whether AFP plays a role in promoting metastasis of HCC cells remains poorly understood." (PMID 26756858, 2016). "Finally, DKK1, an antagonist of the Wnt signalling pathway, was demonstrated to complement AFP in HCC diagnosis particularly in AFP-negative cancers." (PMID 27219517, 2016). "In patients with elevated AFP > 200 or rising AFP but without any measureable disease burden 11C-acetate opens up the possibility of detecting occult or subclinical cancer within a high risk diseased liver." (PMID 25981587, 2015). "The AFP telomerase also plays an extratelomeric role in cancer cells." (PMID 25822740, 2015). "However, there was little difficulty in the diagnosis of the primary cancer which was confirmed by typical findings at liver dynamic CT and MR liver and the elevated AFP level." (PMID 26635983, 2015). "Some cases of recurrence may present with malignant tumors and distant metastasis, and close follow-up with serial AFP monitoring should be done for 5 years." (PMID 26504900, 2015). "The majority of AFP-producing cancers originate from the stomach, bile duct, and pancreas." (PMID 25962419, 2015). "En revanche, l’élévation de l'AFP dans le sang dépend du stade pathologique du cancer." (PMID 25400847, 2014). "Three different cancer biomarkers (AFP, CEA, VEGF) were used to compare the analytical performance and evaluate the efficiency, feasibility, sensitivity, and stability of electrospun PS substrates before or after plasma compared with the conventional PS substrates." (PMID 24340065, 2013). "With FokI CC as reference, our data showed that the TT carriage had a significantly higher risk for development of HCC after adjustments with age, gender, HBV infection time, smoker status, family cancer history, alcohol intake, BMI, and serum AFP level (OR = 2.269, P = 0.006)." (PMID 23586065, 2013). "The immunoassay was evaluated by analyzing three different cancer biomarkers (AFP, CEA, VEGF)." (PMID 24340065, 2013). "Of the patients with malignant tumors, 73.7% had abnormal AFP and CA125 levels." (PMID 23826706, 2013).
cancer (continued). "In the pathological state of chronic liver disease, particularly, that associated with a high degree of hepatocyte regeneration, AFP can be expressed in the absence of cancer." (PMID 23519638, 2013). "ACC is defined as a carcinoma exhibiting evidence of pancreatic enzyme production by the neoplastic cells and may secrete AFP, endocrine products or lipase into the circulation." (PMID 23426888, 2013). "By using the Cancer Targeting Gene-Viro-Therapy strategy, Apoptin, a promising cancer therapeutic gene was inserted into the double-regulated oncolytic adenovirus AD55 in which E1A gene was driven by alpha fetoprotein promoter along with a 55 kDa deletion in E1B gene to form AD55-Apoptin." (PMID 22321574, 2012). "In a previous study, we used AFP-DC as a cancer vaccine to evaluate the antitumor response." (PMID 23170121, 2012). "The novel approach of AFP enhancer/pgk promoter-driven expression of DN-PP2Acα may provide a useful cancer gene therapy strategy to selectively target HCC." (PMID 23173703, 2012). "In fact, GPC3 may be reactivated in HCC as frequently as AFP, which has been used extensively as a marker of this cancer." (PMID 22087143, 2011). "Thus the development of ultrasensitive detecting methods for trace levels of AFP in human serum is important for the early diagnosis of cancers." (PMID 22164043, 2011). "Immunohistochemically, the carcinoma with hepatoid features was diffusely stained for α fetoprotein (AFP), HepPar-1 and Hepatocyte-cell antibodies, but not for Keratin7, whereas the well-differentiated adenocarcinoma was immunoreactive for Keratin7 but not for AFP or Hepatocyte-cell." (PMID 21914163, 2011). "It has been shown that it is potential tumor suppressor genes that repress alpha-fetoprotein (AFP) whose altered expression may lead to development of carcinoma in various tissues." (PMID 20433734, 2010). "Our data imply that the limitation of low specificity of AFP in diagnosing small HCC might be compensated by microsatellite analysis on cell-free DNA in cancer patients." (PMID 12454776, 2002). "Furthermore, we found that EpCAM-positive HCC cells exhibit features of cancer stem cells (CSCs), which are believed to play essential roles in cancer initiation, maintenance, drug resistance, and distant metastasis, as they express high levels of AFP." (PMID 41140754, 2026). "Similarly, another study revealed that AFP levels lack prognostic significance in patients with HCC with small cancer size (≤3 cm in diameter) who underwent curative treatments, including liver transplantation, liver resection, or radiofrequency thermal ablation." (PMID 40429981, 2025). "However, while AFP vaccination may contribute to extended survival in patients with advanced cancer, full-length glycosylated AFP has been reported to exert immunosuppressive effects that can directly promote cancer growth and MDSCs in some cancers." (PMID 40430002, 2025). "This suggests that AFP production may directly correlate with cancer progression and metastasis." (PMID 40430002, 2025). "Moreover, high expression of CSC markers is significantly correlated with cancer grade, stage, AFP serum level, malignancy potential, high recurrence rate and short overall survival, and HBx induces hepatocarcinogenesis closely related with reprogramming of glucose metabolism." (PMID 40717222, 2025). "The nanoprobe is composed of polyethyleneimine-coated PLNP (PEI-PLNP) as an energy donor and AFP antibody-modified gold nanoparticles (Ab-AuNPs) as an acceptor coupled to each other for the detection of AFP in serum samples and for the detection of AFP excreted during the growth of cancer cells." (PMID 40942360, 2025). "A ferrocene-CB7 complex could be used as an electrochemical marker within a sandwich immunoassay and DNA barcoding protocol for a range of cancer biomarkers, allowing for the detection of marker proteins such as alpha-fetoprotein at potentially subfemtomolecular levels." (PMID 37998127, 2023).
cancer (continued). "Furthermore, well-known core fucosylated cancer biomarkers α-fetoprotein (AFP) and α–1-antitrypsin (A1AT), both >50 kDa, displayed systemic elevation in LC patient sera following osimertinib treatment and in secretomes of drug-stressed cells and DR clones, at least those expressing basal A1AT." (PMID 36961502, 2023). "Nanocomposites could also be made of CuO2/graphene oxide/β-cyclodextrin or ferrocene carboxylic acid/graphene oxide/β-cyclodextrin and used as substrates to immobilise antibodies to the cancer biomarkers alpha-fetoprotein (AFP) and carcinoembryonic antigen (CEA)." (PMID 37998127, 2023). "Furthermore, AFP is an independent risk factor for recurrence-free survival, log10AFP is an independent risk factor for cancer-specific survival, while LI-RADS did not have any significant impact on it." (PMID 35326644, 2022). "Alpha-fetoprotein (AFP) has been extensively applied in the diagnosis of various cancers, but due to its low accuracy, specificity, and sensitivity, it is not used in the diagnosis of cancer alone, but in combination with other diagnostic methods." (PMID 36232692, 2022). "Some studies reported that high levels of AFP in the blood could be a sign of certain cancers." (PMID 36557345, 2022). "Therefore, bioinformatics and GO functional enrichment analyses of SLiMs allows insight into the common functions of a variety proteins and the involvement of AFP in cellular response to external and internal stimuli during embryonic development and cancer growth." (PMID 36670957, 2022). "Thus, an AFP vaccine promotes a longer survival of advanced patients with cancer." (PMID 33898423, 2021). "AFP inhibits the maturation of dendritic cells (DC) and induces their apoptosis, so that antigens cannot be presented to T cells by DC cells, thereby freeing cancer cells from immune surveillance, indicating that IL‐18 does not participate in this cellular immune process." (PMID 33720453, 2021). "Indeed, some of the previously reported AFP-producing “endometrioid” carcinomas might fit this description." (PMID 34977100, 2021). "However, in view of the low RAR protein showed in the ChIP assay, binding is significantly reduced in the cancer tissues, which suggests that the interaction between elevated AFP in cytoplasm and RAR results in the reduction of RAR translocation to the nucleus." (PMID 33090723, 2020). "In this way, we may overcome the immune tolerance of AFP and eliminate the cancer cells." (PMID 29805966, 2018). "Notably, these cancers resemble human AFP-producing cancer, one of the most fatal adult cancers, suggesting that epigenetic reorganization related to late-stage reprogramming may be involved in such cancers." (PMID 29802314, 2018). "In addition to offering potential oxidative susceptibility protection to ACA via its hydrophobic pockets, rhAFP also allows for a more specific targeting of cancer cells by chaperoning ACA towards malignant cells which are positive for the AFP cell surface receptor." (PMID 26158863, 2015). "In addition, the overexpression of AFP promotes the proliferation of normal and cancer cells, which indicates that AFP may be involved in cancer liver progression." (PMID 25822740, 2015). "Downregulating AFP expression may be an effective approach to AFP-producing cancer." (PMID 23382965, 2013). "The application of graphene-gold hybrid SPR biosensors in multiplexed systems has been demonstrated for various clinical applications, including the simultaneous detection of cancer biomarkers such as CEA and AFP." (PMID 40559306, 2025). "Although biomarkers, such as alpha-fetoprotein (AFP), prostate-specific antigen, and carcinoembryonic antigen, are used to diagnose and predict treatment responses in specific cancers, their overall sensitivity and specificity are limited." (PMID 40923024, 2025).
cancer (continued). "Our current study investigates the trends and the pattern of HCC in Madinah City of Saudi Arabia and the effect of TNM staging, AFP level, and CTP on cancer progression and patients’ survival." (PMID 39735678, 2025). "A palpable mass is identified in the right abdominal quadrant in 5-30% of patients, associated with or without elevated serum levels of carcinoembryonic antigen (CEA) and cancer antigen 19-9 (CA19-9) and normal alpha fetoprotein (AFP) levels." (PMID 39813555, 2025). "Various biomarkers such as carcinoembryonic antigen (CEA), alpha-fetoprotein (AFP), prostate-specific antigen (PSA), and prostate cancer antigen 3 (PCA3) have been widely identified as vital indicators for early cancers." (PMID 40047709, 2025). "As expected, AFP, a marker for HCC, and CA19‐9 for PAC, showed increases in patients with their respective cancers (AUC = 0.813 and 0.864, respectively)." (PMID 40589150, 2025). "Serum cancer markers such as carcinoembryonic antigen (CEA), alpha-fetoprotein (AFP) and carbohydrate antigen 125 (CA125) are common and useful markers for assessing the risk of tumors." (PMID 40535138, 2025). "A 2023 study reported the presence of SPP1-expressing TAM in alpha-fetoprotein-positive HCC tissues and demonstrated that SPP1 can inhibit the anti-cancer activity of T cells by binding to CD44." (PMID 38757323, 2025). "They administered 5 and 10 mg/kg ZnO-NPs daily for 8 weeks and found that the treatment of these animals with these NPs resulted in the inhibition of cancer biomarkers including glypican-3 (GPC3), VEGF, and alpha-fetoprotein (AFP)." (PMID 40182988, 2025). "For diagnostics of cancer, a variety of protein biomarkers have been identified, such as KRAS for pancreatic cancer, HER2 for breast cancer, AFP for liver cancer, and PSA for prostate cancer." (PMID 40559306, 2025). "Interactions between branched-chain amino acid (BCAA) metabolism and AFP levels have been observed in patients with hepatitis C virus infection, suggesting that increased breakdown of BCAAs might provide an enhanced energy supply to rapidly dividing cancer cells." (PMID 40430002, 2025). "These preclinical results highlight the potential of AFP-based vaccines for immunotherapy and provide important foundational data for inducing immune responses in the treatment of HCC and other cancers." (PMID 40430002, 2025). "The device was used to simultaneously detect four cancer biomarkers—CEA, AFP, CA125, and CA153—with a short analysis time." (PMID 38999110, 2024). "This biosensor was manufactured for the detection of alpha-fetoprotein (AFP), which is known as a biomarker of cancer." (PMID 38396756, 2024). "Cancer stem cells (CSCs) isolated from HCC are characterized by the expression of stem cell markers CD44, CD133 and alpha‐fetoprotein (AFP), and inhibition of these markers has been regarded as a reliable indicator for response to chemotherapy." (PMID 38722284, 2024). "This association remained significant after further adjustment for cancer treatment, ALBI grade, and AFP level (aHR = 0.64, 95% CI: 0.47–0.87)." (PMID 38965335, 2024). "Transcriptome analysis revealed a set of significantly differentially expressed secreted genes, including AFP, MMP9, MMP-7, and S100A9, which are known regulators of cancer progression and therapeutic targets in cancer patients." (PMID 38307859, 2024). "Comprehensive serological examinations, including ferritin (FER), carcinoembryonic antigen (CEA), alpha-fetoprotein (AFP), carbohydrate antigen 19-9 (CA19-9), cancer antigen 125 (CA125), and cancer antigen 15-3 (CA15-3), were all within normal limits." (PMID 39533578, 2024).